RNU6-1162P (RNA, U6 small nuclear 1162, pseudogene)
Gene: Small nuclear RNA gene on chromosome 14 (63,630,678 to 63,630,781, forward strand). Ensembl gene ENSG00000207172.
Homologues: Orthologues: chimpanzee U6 (100% identical), dog U6 (87% identical), mouse Gm25740 (83% identical), rat LOC120103229 (65% identical). Paralogues in human: RNU6-1145P (88% identical), RNU6-1316P (87% identical), RNU6-38P (87% identical), RNU6-393P (87% identical), RNU6-639P (87% identical), RNU6-836P (87% identical), RNU6-1031P (86% identical), RNU6-1214P (86% identical), RNU6-144P (86% identical), RNU6-20P (86% identical), RNU6-214P (86% identical), RNU6-39P (86% identical), and 1284 more.